RNU6-882P (RNA, U6 small nuclear 882, pseudogene)
Gene: Small nuclear RNA gene on chromosome 3 (9,919,051 to 9,919,153, reverse strand). Ensembl gene ENSG00000212327.
Homologues: Orthologues: chimpanzee U6 (100% identical), macaque U6 (96% identical), dog U6 (75% identical). Paralogues in human: RNU6-38P (85% identical), RNU6-1145P (83% identical), RNU6-29P (83% identical), RNU6-393P (83% identical), RNU6-434P (83% identical), RNU6-618P (83% identical), RNU6-73P (83% identical), RNU6-1011P (83% identical), RNU6-1316P (83% identical), RNU6-16P (83% identical), RNU6-20P (83% identical), RNU6-25P (83% identical), and 1285 more.